GDF7 (growth differentiation factor 7)
Description:
May play an active role in the motor area of the primate neocortex.
Synonyms: BMP12
Tractability: Antibody: UniProt places it where antibodies can reach, with medium confidence; UniProt predicts a signal peptide or a membrane-spanning region; its Gene Ontology location is reachable by antibodies, with medium confidence.
Gene: Protein-coding gene on chromosome 2 (20,667,144 to 20,679,243, forward strand). Ensembl gene ENSG00000143869.
Subcellular location: Secreted
Subcellular location (Human Protein Atlas): Vesicles; Predicted to be secreted
Gene Ontology:
Molecular function: protein binding; cytokine activity; growth factor activity; identical protein binding
Biological process: activin receptor signaling pathway; BMP signaling pathway; positive regulation of DNA-templated transcription; positive regulation of SMAD protein signal transduction; positive regulation of gene expression; positive regulation of tendon cell differentiation; regulation of transmembrane receptor protein serine/threonine kinase signaling pathway
Cellular component: extracellular region
Genetic constraint (gnomAD): Loss-of-function variants: 12 observed, 10.89 expected, observed/expected ratio (o/e) 1.1, 90% interval 0.7 to 1.73. The synonymous counts are far from expectation, so gnomAD's model fits this gene poorly and the ratio says little. Missense variants: 588 observed, 458.86 expected, observed/expected ratio (o/e) 1.28, 90% interval 1.2 to 1.37. Synonymous variants: 294 observed, 215.36 expected, observed/expected ratio (o/e) 1.37, 90% interval 1.24 to 1.5.
Homologues: Orthologues: chimpanzee GDF7 (98% identical), pig GDF7 (86% identical), rat Gdf7 (83% identical), dog GDF7 (83% identical), mouse Gdf7 (83% identical), macaque GDF7 (74% identical), rabbit GDF7 (70% identical), tropical clawed frog gdf7 (43% identical), zebrafish gdf6a (41% identical), zebrafish gdf7 (41% identical), zebrafish gdf6b (38% identical). Paralogues in human: GDF6 (44% identical), GDF5 (39% identical), BMP2 (26% identical), BMP10 (25% identical), BMP4 (25% identical), BMP6 (23% identical), GDF2 (23% identical), BMP7 (22% identical), BMP8A (22% identical), BMP8B (22% identical), BMP5 (21% identical), GDF1 (19% identical), and 19 more.
Diseases named in the same sentence as GDF7 in open-access papers:
GDF7 is named in the same sentence as 26 diseases in open-access papers, as found by Europe PMC text mining. Sharing a sentence is not in itself a finding about the gene and the disease. The quoted sentences say what the papers report.
esophageal adenocarcinoma (8 papers, 2015 to 2025). A malignant tumor with glandular differentiation arising predominantly from Barrett mucosa in the lower third of the esophagus. "Rs3072 at GDF7 was associated with the progression of esophageal adenocarcinoma." (PMID 36910333, 2023). "In addition, a variant in GDF7 (rs3072) has been reported to increase risk for Barrett’s esophagus and esophageal adenocarcinoma." (PMID 32575532, 2020).
Barrett esophagus (6 papers, 2015 to 2025). Esophageal lesion lined with columnar metaplastic epithelium which is flat or villiform. "GDF7 encodes BMP12, part of the bone morphogenetic protein pathway, and is heavily implicated in Barrett’s oesophagus with several studies identifying polymorphisms in the TBX-GDF7 genomic region." (PMID 36584111, 2022).
endometrial cancer (3 papers, 2021 to 2025). Primary or metastatic malignant neoplasm involving the endometrium (mucous membrane that lines the endometrial cavity). "In the current study, we found that GDF7 was also significantly downregulated in endometrial cancer." (PMID 34925436, 2021). "employed transcriptome sequencing technology to analyze 5 pairs of endometrial cancer tissues and normal endometrial tissues, revealing downregulation of ID1, IGF1, GDF7, SMAD9, TGF-β, and WNT4 expression alongside upregulation of GDF5, INHBA, and ERBB4 in endometrial cancer." (PMID 38239355, 2023).
glaucoma (3 papers, 2024 to 2026). Increased pressure in the eyeball due to obstruction of the outflow of aqueous humor. "TET-dependent GDF7 hypomethylation increases GDF7 expression and can serve as a potential therapeutic target in glaucoma." (PMID 38915445, 2024). "The proof-of-concept studies of GDF7 neutralization in primate models and the OSK-factor reprogramming in aged and glaucoma mice models, show that epigenetic changes are reversible and can restore visual functions." (PMID 41809128, 2026). "In primary open-angle glaucoma, the TET enzyme maintained the hypomethylation of the GDF7 promoter in trabecular meshwork (TM) cells, thereby activating the bone morphogenetic protein receptor type 2 and Smad signaling pathways." (PMID 39678047, 2024).
medulloblastoma (3 papers, 2012 to 2025). A malignant, invasive embryonal neoplasm arising from the cerebellum. "Collectively, these data indicate that targeting constitutively active Shh signaling to the Gdf7-lineage leads to the formation of medulloblastoma." (PMID 22539980, 2012). "Our findings uncover a broad contribution of Gdf7-lineage to the cerebellum and suggest that medulloblastoma can stem from progenitor populations that were previously thought to be restricted to the choroid plexus lineage." (PMID 22539980, 2012). "We demonstrate here that constitutive activation of the Sonic hedgehog signaling pathway in the Gdf7 lineage invariably leads to medulloblastoma." (PMID 22539980, 2012). "Here we show that ectopic Shh signaling in the Gdf7-lineage cells invariably led to formation of medulloblastoma with CGNP features, indicating that focal activation of the Shh signaling pathway in the Gdf7-lineage cells is sufficient to promote cerebellar tumorigenesis." (PMID 22539980, 2012).
abdominal aortic aneurysm (1 paper, 2022). Enlargement and ballooning of the vessel that supplies arterial blood to the abdomen, pelvis and legs. "GDF7 has been identified through GWAS to associate with eight traits, three of which are characterised by connective and elastic tissue dysfunction: pelvic organ prolapse, abdominal aortic aneurysm, and diverticular disease." (PMID 36584111, 2022).
colorectal cancer (1 paper, 2021). A primary or metastatic malignant neoplasm that affects the colon or rectum. "An earlier study found that GDF7 was downregulated in colorectal cancer tissues." (PMID 34925436, 2021).
Hernia (1 paper, 2022). "GDF7 was discovered to associate with hernia in the umbrella and metaUSAT analyses, with the lead variant rs3072 demonstrating strong functionality as a robust eQTL for GDF7 in GTEx aorta tissue (PeQTL = 5.4×10−9)." (PMID 36584111, 2022).
Hydrocephalus (1 paper, 2020). Hydrocephalus is an active distension of the ventricular system of the brain resulting from inadequate passage of CSF from its point of production within the cerebral ventricles to its point of absorption into the systemic circulation. "Furthermore, GDF7-null mutant mice show hydrocephalus, and they show considerable variation in the location of the dilated ventricle." (PMID 32575532, 2020).
liver fibrosis (1 paper, 2023). "Here, we examined hepatic GDF7 expression and its association with development and progression of human liver fibrosis." (PMID 37798809, 2023). "Collectively, this study reveals a role of GDF7 in liver fibrosis and suggests a potential pro-regenerative function that can be utilized for amelioration of hepatic fibrosis caused by chronic liver disease." (PMID 37798809, 2023). "Our data show that GDF7 expression is strongly upregulated in human fibrotic livers, which aligns with increased GDF7 gene expression in blood cells in patients with liver fibrosis reported by others." (PMID 37798809, 2023). "Potential effects of GDF7 on other cell types in liver fibrosis remain to be determined in future studies." (PMID 37798809, 2023). "For example, applying recombination human GDF7 or activation of GDF7 receptors and downstream pathways are potential therapeutic approaches to promote liver regeneration in patients with liver fibrosis." (PMID 37798809, 2023). "This study shows that hepatic GDF7 expression positively correlates with the progression of human liver fibrosis." (PMID 37798809, 2023). "Moreover, HSC-induced expression of GDF7 in hepatocytes and cholangiocytes likely ends up in circulation, and together with enhanced GDF7 expression by blood cells may serve as a marker of liver fibrosis." (PMID 37798809, 2023).
lupus (1 paper, 2022). "Thus, the downregulation of GDF7 in CD4+ T cells may lead to impaired suppressive functions of lupus Tregs." (PMID 36046235, 2022).
Stroke (1 paper, 2019). Sudden impairment of blood flow to a part of the brain due to occlusion or rupture of an artery to the brain. "We found two members of this family to be upregulated in the stroke-denervated spinal GM: GDF7 and TGF-β1." (PMID 30962276, 2019). "Furthermore, four upregulated candidates were addressed in this study as potential stroke-induced growth-promoters: Sema6a, Ntng2, GDF7, and TGF-β1." (PMID 30962276, 2019).
tendinopathy (1 paper, 2025). "Autologous mesenchymal/stromal stem cells (MSCs) and tendon-derived stem cells (TSCs), combined with growth factors (GFs) like GDF-5, GDF-6 and GDF-7, are emerging as potential therapies for tendinopathy." (PMID 40395976, 2025).
cancer (5 papers, 2019 to 2025). A tumor composed of atypical neoplastic, often pleomorphic cells that invade other tissues. "Our analysis identified cancer as one of the top diseases associated with the significantly differentially expressed lncRNAs and mRNAs and revealed the integrated link between the gene/lncRNA pairs: CBL/T216482 and GDF7 (BMP12)/T185733, prominently associated in cancer pathways." (PMID 31324852, 2019). "GDF7 is a ligand in the BMP pathway that has been known to have inhibitory effects on growth in various human cancers." (PMID 34925436, 2021). "GDF7 was one of the top candidate genes among the cancer related molecules." (PMID 31324852, 2019).
tumor (5 papers, 2012 to 2025). "In one tumor with MNA and its associated cell line, a few novel amplicons were found, which encompassed genes such as GDF7, FSHR, PRKCE, and TMEM18." (PMID 23656755, 2013). "Furthermore, YFP expression covering most of the cerebellar surface in the Gdf7Cre/+;SmoM2 mice suggests that the tumor cells are derived from Gdf7-expressing progenitor cells." (PMID 22539980, 2012). "The lack of apparent Gdf7 and Msx1 expression in the Math1+ tumor tissue of Gdf7Cre/+;SmoM2 mice argues against this possibility." (PMID 22539980, 2012).
adenocarcinoma (1 paper, 2016). A common cancer characterized by the presence of malignant glandular cells. "GDF7 is known to play an important role in growth, repair, and embryonic development, and its polymorphism leads to adenocarcinoma." (PMID 27777635, 2016).
GDF7 also shares sentences with these, for which no sentence is quoted: Sepsis (2 papers); acute lung injury (1); choroid plexus papilloma (1); diverticular disease (1); infection (1); pelvic organ prolapse (1); primary open-angle glaucoma (1); prostate carcinoma (1); type 2 diabetes (1); Ventriculomegaly (1).